ENSG00000276302 (novel protein)
Gene: Protein-coding gene on chromosome 6 (28,267,121 to 28,281,580, forward strand). Ensembl gene ENSG00000276302.
Genetic constraint (gnomAD): Loss-of-function variants: 7 observed, 4.86 expected, observed/expected ratio (o/e) 1.44, 90% interval 0.77 to 1.92. That is too few expected variants to judge how well the gene tolerates losing a copy. Missense variants: 42 observed, 50.68 expected, observed/expected ratio (o/e) 0.83, 90% interval 0.65 to 1.07. Synonymous variants: 14 observed, 15.98 expected, observed/expected ratio (o/e) 0.88, 90% interval 0.58 to 1.37.